IL10 (interleukin 10)
Diseases named in the same sentence as IL10 in open-access papers (continued):
Sharing a sentence is not in itself a finding about the gene and the disease.
Autoimmunity (continued). "This microRNA is a proinflammatory NF-κB-induced miRNA associated with T cell-dependent inflammation and autoimmunity, and expression is suppressed by IL-10." (PMID 24967703, 2014). "Administering recombinant IL-10 or employing agents to stimulate its endogenous production in Bregs could counteract the autoimmunity associated with T1DM." (PMID 40370441, 2025). "Maintaining tight regulation of TNFα may require more inhibitors like IL-10 for maturing women and be part of their susceptibility to autoimmunity." (PMID 36793337, 2023). "IgD+CD27+ unswitched MBCs decrease is an early feature of pSS correlated with serological autoimmunity and disease progression, and represents the loss of a MZ-equivalent endowed with protective functions such as apoptotic clearance, Interleukin-10-mediated B regulatory activity." (PMID 34603334, 2021). "In addition, CD21low B cells produce significantly higher amounts of IgM as compared to näive B cells upon stimulation with CD40L, IL-2 and IL-10, and higher IgM levels have been associated with the development of autoimmunity in CVID patients." (PMID 34290696, 2021). "Notwithstanding, studies in MRL-Faslpr mice revealed that during the initial phases of the disease, IFN-γ and its induced IgG2a promote autoimmunity, and IL-10 appears to be needed to suppress such pathogenic TH1 responses, including IFN-γ-mediated autoantibody production and renal inflammation." (PMID 34705865, 2021). "Moreover, it is likely that other anti-inflammatory mediators originated from Breg cells can compensate the loss of IL-10 in regulating autoimmunity." (PMID 33240280, 2020). "HTLV-1-induced changes in the activity of regulatory CD4 T-cell molecules affect the homeostasis of cytokines, including IFN- γ, TNF-α, TGF-β and IL-10, and disrupt the balance in inflammatory and anti-inflammatory responses, leading to the loss of tolerance and the development of autoimmunity." (PMID 26712781, 2015). "Here, we have shown a numerical and functional impairment in the subset of IL10-producing B cells with age, and we thus questioned whether this impairment may contribute towards increased risk of autoimmunity with age." (PMID 23755918, 2013). "It is tempting to speculate that the strategy of the immune system to counteract age associated increased risk of autoimmunity is promotion of differentiation of T cells with a potential to secrete IL-10 (so called Tr1 cells)." (PMID 22321827, 2012). "IL-10 is capable of inhibiting the synthesis of proinflammatory cytokines, while IL-12 is linked to autoimmunity by stimulating the production of interferon-gamma (IFN-γ) and tumor necrosis factor-alpha (TNF-α) from T and natural killer (NK) cells, and by reducing IL-4-mediated suppression of IFN-γ." (PMID 20379374, 2010). "Furthermore, this autoimmunity may be linked to increased numbers of regulatory T cells (Treg) and immunoregulatory cytokines (e.g., IL-10 and TGF-β), which contribute to impaired T-cell responses in CHC." (PMID 40181970, 2025). "Indeed, NOD mice deficient in il-10 were protected from organ-specific autoimmunity; therefore, in our experimental setting, the increase in il-17 and il-10 transcript levels in opn-deficient mice correlated with the T1D acceleration observed after infection by the parasites." (PMID 39436890, 2024). "Additionally, sex hormones such as testosterone can increase the production of anti-inflammatory IL-10 and provide protection against autoimmunity; however, the effects of such hormones in females change after puberty which raises autoimmunity risk and disease prevalence." (PMID 36902168, 2023). "Hence, HTLV-1-induced changes in regulatory CD4 T-cell molecules activity affects the homeostasis of cytokines such as IFN-γ, TNF-α, TGF-β, and IL-10, which disrupts the balance in anti-inflammatory and inflammatory responses, resulting in the loss of tolerance and the development of autoimmunity." (PMID 37293205, 2023).
Autoimmunity (continued). "Moreover, the microbiomes of MS-twins can provoke autoimmunity accompanied by paralyzed production of the anti-inflammatory IL-10 following transplantation in susceptible animal models, fueling the idea of the pathogenic role of the gut microbiome mediated via immunological elements in MS." (PMID 38132289, 2023). "Therefore, IL-10 may also play a role in the production of pathogenic IgG4 in patients, together with further factors that may predispose to develop autoimmunity." (PMID 35095860, 2021). "The increased risk of autoimmunity in patients with TS has also been attributed to X-chromosome haploinsufficiency, maternal origin of the X-chromosome, excessive production of proinflammatory cytokines (IL-6), decrease in anti-inflammatory cytokines (IL-10, TGF-β), or hypogonadism." (PMID 29915563, 2018). "However, Th2-type cytokines (such as IL-4, IL-5, IL-10, etc.)can lead to less autoimmunity, susceptible to infections, and also may induce pregnancy-tolerance to fetus, providing protection to pregnancy." (PMID 25563385, 2015). "However, it is still controversial whether IL-10 attenuates autoimmunity by blocking IFN-mediated autoimmune-associated inflammation in lupus." (PMID 23800014, 2013). "IL10 is another cytokine that enhances B-cell activity and is associated with TH1-driven autoimmunity in SjD." (PMID 41181128, 2025). "In T1DM, Bregs mitigate β-cell autoimmunity via IL-10 production and FOXP3-mediated pathways, but genetic mutations and dysfunctions in these mechanisms exacerbate autoimmunity." (PMID 40370441, 2025). "Of note, patients with autism have increased inflammatory cytokines IL-21, IL-22, IFN-γ, and IL-4 from T cells, decreased antiinflammatory cytokines TGFβ and IL-10, two functional cytokines produced by Tregs, activated T cells, and/or autoimmunity." (PMID 40155813, 2025). "Transitional B cells and IL-10-producing B cells which are antiinflammatory B lymphocyte subsets are well recognized in the field of autoimmunity as important checkpoint regulators of autoreactive T cells." (PMID 40230858, 2025). "Interleukin-10 is an anti-inflammatory cytokine with roles in autoimmunity, cancer, and homeostasis." (PMID 39861482, 2025). "FXR attenuated neuroinflammation through interleukin‐10 (IL‐10)‐dependent promotion of macrophage type 2 (M2) macrophage polarisation and suppression of T cell‐mediated autoimmunity." (PMID 40717237, 2025). "The ability of DC-SIGN+ cells to produce IL-10 underscores their importance in both preventing autoimmunity and supporting appropriate immune responses against pathogens." (PMID 40076949, 2025). "In our study, macrophages isolated from RA patients expressed significantly lower levels of IL‐10 than those from HC across all treatment groups, indicating the importance of this cytokine in RA autoimmunity." (PMID 40099178, 2025). "The relationship between vitamin D and autoimmunity can compromise the development of Th17 cells while increasing the production of IL-10." (PMID 39861482, 2025). "Unlike the pro-inflammatory CXCL10, CXCL11 promotes the development of IL-10–producing regulatory T cells, which help control autoimmunity." (PMID 40969764, 2025). "Some molecules from MDSCs (Arg-1, PGE2, miR-29a-3p, and miR-93-5p) have been reported to inhibit T cell responses and promote IL-10+ Breg cell generation in autoimmunity, consistent with MDSC suppressive activity." (PMID 37733169, 2024). "In heart recipients with coronary artery vasculopathy, T cells tend to produce less IL-10 and more IL-17 and IFNγ, indicating a Th17 response that promotes autoimmunity." (PMID 39408890, 2024). "IL-6 produced from B cells provoked pathogenesis in EAE, whereas IL-10-producing B cells protected against autoimmunity in EAE." (PMID 38213874, 2024). "IL-10 is a key factor in inhibiting inflammatory response and plays a pivotal role in regulating immune responses and preventing autoimmunity." (PMID 38312681, 2024).
Autoimmunity (continued). "In T1D, differential regulation of il-10 has been reported, and a role for this gene in the modulation of both innate and adaptive immune cells and the development of autoimmunity has been proposed." (PMID 39436890, 2024). "Activation of iNKT cells by αGalCer expands innate IL-10 producing MZBs, which suppress autoimmunity through IL-10 secretion." (PMID 38993780, 2024). "Both IL1-RA and IL-10 play a crucial role as an anti-inflammatory cytokine, possessing the ability to curb inflammatory and autoimmune disorders." (PMID 38675216, 2024). "In fact, IL-10, including IL-10 produced by Tr1 cells, has been involved in the anti-inflammatory function in autoimmunity, viral/bacterial infections, and allograft transplantation." (PMID 38250904, 2024). "B1 and MZB cells in mice are seen to play a key role in autoimmunity mitigation by producing regulatory cytokines (IL-10) and natural antibodies (IgM) although the mechanisms involved are not well established in MS." (PMID 38213874, 2024). "Type III IFN and cytokines IL-10, IL-22, and IL-26 are ligands for this receptor, thereby linking the genetic overdosage in trisomy 21 with autoimmunity and autoinflammation in DS." (PMID 39457216, 2024). "Plasma cells or plasmablasts have also been found to be an important source of IL-10 in response to infection or in autoimmunity." (PMID 38487540, 2024). "Conversely, regulatory B cells that produce IL-10 inhibit Tfh cell responses in SS, indicating that fine-tuning of B cell responses is crucial for controlling autoimmunity and T cell reactions in the syndrome." (PMID 39290700, 2024). "While the increased frequency of Tr1 cells and elevated IL-10 levels suggest attempts at immune regulation, the persistence of autoimmunity indicates that these mechanisms are insufficient to fully control the disease process." (PMID 39211721, 2024). "This combination of 13 features suggests on the one hand a systemic inflammation and autoimmunity, signaled by neutrophils and autoantibodies, and on the other hand an immune paralysis and anti-inflammatory effort (i.e. steroid therapy, IL-10)." (PMID 38730063, 2024). "These different IL-10+ Breg populations are represented across the spectrum of immunological tolerance in transplantation, autoimmunity, inflammation, cancer and infection." (PMID 39346706, 2024). "CD56bright NK cells are able to produce IFN-γ and IL-10 alternatively depending on their environment and were proposed to play a protective role in autoimmunity." (PMID 38667291, 2024). "Such cells are characterized by increased expression of the immunoregulatory genes Il10, Il9, Maf, and Ahr; produce cytokine IL-17 and high doses of the anti-inflammatory cytokine IL-10; and have a weak ability to trigger autoimmunity." (PMID 38067176, 2023). "As both testosterone and estrogen upregulate IL-10 in some capacity, it is unlikely that IL-10 drives the sex bias of autoimmunity." (PMID 36793337, 2023). "High levels of mouse interleukin 10 (mIL-10) achieved following rAAV2-IL-10 intramuscular administration also proved to have a positive effect in NOD mice by decreasing autoimmunity, and thereby hyperglycemia." (PMID 36899921, 2023). "Overall, these findings suggest the importance of cAMP/PKA signaling in the development of autoimmunity in CVID, as diminished IL-10 levels produced by Tregs represent a mechanism that promotes autoimmunity." (PMID 36834508, 2023). "Lactic acid bacteria have been shown to prevent intestinal inflammation and autoimmunity by increasing IL-10 and CD4+ CD25+ Treg cells." (PMID 37894114, 2023). "With these data in mind, we propose a model whereby environmental factors operate through the gut microbiota promote IL-10+ B cell populations with the capacity to directly or indirectly regulate CNS autoimmunity during MS and EAE." (PMID 37600781, 2023).
Autoimmunity (continued). "As a prototypical anti-inflammatory mediator, IL-10 plays an essential role in protection from over-exuberant responses to pathogens and microbiota in autoimmunity, cancer, and homeostasis." (PMID 37492521, 2023). "Evidence that host commensal microbial communities influence IL-10 levels and subsequently CNS autoimmunity was first derived from antibiotic treatment studies." (PMID 37600781, 2023). "IL-4 and IL-10 are the main cytokines that regulate the functions of Th2 and provide beneficial effects against autoimmune disorders." (PMID 37111711, 2023). "The relative protection afforded by the non-MS twin FMT was abrogated by administration of an anti-IL-10 neutralizing antibody, indicating that the FMT influenced CNS autoimmunity in an IL-10 dependent manner." (PMID 37600781, 2023). "Regulatory B cells (Bregs) expressing IL-10 and other inhibitory cytokines, play a critical role maintaining self-tolerance, and can inhibit autoimmunity, allograft and tumor rejection, and anti-microbial responses." (PMID 35359977, 2022). "For example, in reporter mice, IL-10-producing B cells were able to suppress the production of pro-inflammatory cytokines and protect against autoimmunity, highlighting their regulatory function." (PMID 35406717, 2022). "IL-10 promotes B cell proliferation and differentiation, and continuous administration of anti-interleukin 10 antibody delays autoimmunity in NZB/W F1 mice by upregulating TNF-α." (PMID 35359961, 2022). "In humans, autoimmunity inflammation, such as lupus, can be reduced when IL-10-producing B cells induce Tregs." (PMID 36618354, 2022). "We also demonstrate the negative regulatory role of IL-10 in C. jejuni induced autoimmunity and provide IL-4 and Siglec-1 blockade as potential therapeutic interventions against GBS." (PMID 35442154, 2022). "Bregs can suppress immune reactivity against exogenous and endogenous antigens and in particular they can act as a cellular brake on the development of autoimmunity, often via IL-10 production." (PMID 35672305, 2022). "The roles of IFNγ and IL-10, expressed respectively by B effector 1 (Be1) and Bregs, have been established in pathogen clearance, tumor growth, autoimmunity and allograft rejection." (PMID 35359977, 2022). "The immunomodulatory cytokine IL-10 plays a critical role in controlling excessive immune responses during infections and autoimmunity, mainly by inhibiting the production of pro-inflammatory cytokines in various cell types." (PMID 35337004, 2022). "By binding to α2,3-sialic acid-decorated CD43/CD45 clusters expressed on DCs, Gal-1 has been shown to support differentiation of tolerogenic DCs, thereby promoting interleukin 10 (IL-10) mediated T cell tolerance and suppression of autoimmunity." (PMID 35833138, 2022). "This is relevant in the context of lupus since Tregs and IL-10 play an established and important immunoregulatory role in constraining the development of autoimmunity." (PMID 36505422, 2022). "Several studies have shown that apoptotic cell-stimulated interleukin-10 (IL-10), a major immunoregulatory cytokine, plays a crucial role in the prevention of autoimmunity." (PMID 35615359, 2022). "Most notably, anti-inflammatory IL-10 and IL-35-producing PCs, which are the main source of these cytokines in models of infection and autoimmunity, expressed IgM at exceptionally high levels." (PMID 35333906, 2022). "It has been described that IL-10-producing plasmablasts exert regulatory functions in autoimmunity and we observed that plasmablasts from T. cruzi-infected mice produce IL-10 (data not shown)." (PMID 35651611, 2022). "Increasing PD-1 expression on the T cell surface contributes to the IL-10 response, T cell activation, immunologic homeostasis and prevents autoimmunity." (PMID 34360926, 2021). "Regulatory B (Breg) cells that produce IL-10 exert potent immunosuppressive functions in patients with allergic and autoimmune disorders." (PMID 34867940, 2021).
Autoimmunity (continued). "PSA augments T-cell PD-1 expression, influencing the IL-10 reaction and T cell stimulation, as well as averting autoimmunity by promoting immune homeostasis." (PMID 34360926, 2021). "Interleukin 10 (IL-10)-producing regulatory T cells (Tregs) are key to immune homeostasis and play opposing roles in autoimmunity versus cancer." (PMID 34335585, 2021). "It is expressed in immune cells including T cells, B cells dendritic cells, and macrophages and contributes to inflammation and induction of autoimmunity via increased expression of proinflammatory cytokines, and inhibition of IL-10." (PMID 34106998, 2021). "During post stroke inflammation, IL-10 seems to directly inhibit the IL-17A production in Th17 cells in ischemic brains, which is a known mechanism from other models of autoimmunity." (PMID 34772416, 2021). "Notwithstanding, it has been observed that continuous administration of anti-IL-10 (TH2) delays the onset of autoimmunity in B x W mice with a suppressive effect of IL-10 in genetically deficient mice of IL-10 MRL-Faslpr." (PMID 34705865, 2021). "In NZB/W F1 mice, the delayed onset of autoimmunity in the presence of neutralizing α-IL-10 was suspected to be due to an up-regulation of endogenous TNF-α." (PMID 33572870, 2021). "Regulatory B cells (Breg) mainly suppress autoimmunity by producing interleukin-10 (IL-10) and through direct interaction with other leukocytes, but their role in atherosclerosis remains controversial." (PMID 34829915, 2021). "Androgen/androgen receptor complexes can directly induce anti-inflammatory IL-10 expression by CD4 + T cells, which has been proposed to underlie male protection from central nervous system (CNS) autoimmunity." (PMID 34930155, 2021). "B regulatory cells are defined functionally by their production of regulatory cytokines such as IL-10 and TGFβ and have been shown to suppress immune responses in autoimmunity models." (PMID 32635160, 2020). "Regulatory T (Treg) cells are an important component of CD4+ T cells that maintain peripheral tolerance and suppress antigen-specific immune responses by secreting transforming growth factor-β (TGF-β), interleukin-10 (IL-10), and IL-4 to inhibit autoimmunity." (PMID 32149142, 2020). "Such inducible Tregs, including Foxp3-positive Tregs induced in the periphery from naïve T cells, IL-10-secreting Type I Tregs, and TGFβ-secreting Th3 cells, have been shown to be able of preventing autoimmunity." (PMID 33202847, 2020). "The frequency of autoimmunity was high among patients with RAG, WAS, STAT5b, NF-κB2, Fas, FasL, LRBA, APECED, IL-10, and C4 deficiencies." (PMID 32582199, 2020). "The miRNA-21 inhibits the differentiation of IL-10+ Breg cells and promotes autoimmunity by targeting the 3′ untranslated region of IL-10 mRNA." (PMID 32582189, 2020). "Bregs are predominately identified on their ability to produce IL-10 which regulates autoimmunity and suppresses T cell and cytokine responses." (PMID 31120872, 2019). "Such mice have been previously used to study the role of intestinal T cell-derived IL-10 in regulating gut inflammation, B cell-derived IL-10 during autoimmunity and IL-10 mediated regulation of liver inflammation during acute MCMV infection." (PMID 31803193, 2019). "Several lines of evidence suggest that CD24hiCD38hi Breg cells and CD24hiCD27+ B10 cells are IL-10-producing B cells with potent regulatory function in autoimmunity, infection, and transplantation." (PMID 31375697, 2019). "Mouse regulatory B cells (IL-10-producing B cells or B10 cells) control T-cell autoimmunity through IL-21-dependent cognate interactions." (PMID 30257456, 2018). "IL-10-producing regulatory B cells (Bregs) are of great importance in autoimmunity, as they inhibit proinflammatory T cells." (PMID 32185301, 2018).